VPS33B (VPS33B late endosome and lysosome associated)
Diseases named in the same sentence as VPS33B in open-access papers (continued):
Sharing a sentence is not in itself a finding about the gene and the disease.
lung adenocarcinoma (1 paper, 2022). A carcinoma that arises from the lung and is characterized by the presence of malignant glandular epithelial cells. "Overexpression of VPS33B has been reported to decrease cell proliferation and chemoresistance in in vitro assays and in vivo mouse studies of lung adenocarcinoma, nasopharyngeal carcinoma, colorectal cancer and ovarian cancer." (PMID 36010647, 2022). "Cell migration and invasion, as well as intrahepatic dissemination and lung metastasis, were also lower when VPS33B was experimentally overexpressed in cell and mouse models of lung adenocarcinoma." (PMID 36010647, 2022).
malignant glioma (1 paper, 2022). A grade III or grade IV glioma arising from the central nervous system. "Therefore, the low expression of CT62, DPY19L2P1, KCNH1‐IT1 and VPS33B in malignant glioma would promote the formation of M2 macrophages and thus promote malignant glioma tumorigenesis and progression." (PMID 35194922, 2022). "Therefore, given that exosomes, a kind of vesicle that mediates communication between cells by transferring ncRNAs, promote tumorigenesis, can VPS33B promote exosomes carrying ncRNAs to other cells in addition to malignant glioma and thus regulate the tumor microenvironment?" (PMID 35194922, 2022). "During the process of illustrating the circadian rhythm pathway, among the 6 coding genes, we exhibited the biological functions of TBPL1, NPAS2, CRY2, and ETNK1; therefore, what are the roles of VPS33B and C9ORF40 in malignant glioma?" (PMID 35194922, 2022). "Fourteen genes within the tumour immune microenvironment pathway (AC020907.1, Y_RNA, TMEM72‐AS1, KRT16P2, DLX6‐AS1, AP002414.1, hsa‐miR‐424, TBPL1, NPAS2, CRY2, VPS33B, CT62, DPY19L2P1, and KCNH1‐IT1) were used to construct a model to evaluate the importance of these genes in malignant glioma." (PMID 35194922, 2022).
nasopharyngeal carcinoma (1 paper, 2019). A carcinoma arising from the nasopharyngeal epithelium. "In this research, we demonstrated that overexpression of VPS33B inhibited proliferation and chemoresistance to fluorouracil (5-FU) in nasopharyngeal carcinoma (NPC) in vivo and in vitro." (PMID 30944308, 2019).
Parkinson disease (1 paper, 2023). A progressive degenerative disorder of the central nervous system characterized by loss of dopamine producing neurons in the substantia nigra and the presence of Lewy bodies in the substantia nigra and locus coeruleus. "The translational profile of striatopallidal neurons is preferentially altered by deep brain stimulation of the subthalamic nucleus in an animal model of Parkinson’s disease, and one of the genes they identified was VPS33B." (PMID 36982508, 2023).
schizophrenia (1 paper, 2026). A major psychotic disorder characterized by abnormalities in the perception or expression of reality. "Placentae from ∆9-tetrahydrocannabinol-exposed males and females revealed altered expression of genes previously identified in human transcriptomic datasets of schizophrenia (i.e., Furin, Rccd1, and Atp5mk), with some expression changes being sex-specific (i.e., Eif5, Rps10, Vps33b, and Iqgap1)." (PMID 40827685, 2026).
sensorineural deafness (1 paper, 2017). "VPS33B is ubiquitously expressed, including expression in the vestibulocochlear ganglion, and disruption of VPS33B-dependent intracellular protein trafficking and collagen homeostasis may also underlie the sensorineural deafness of patients with ARKID and ARC." (PMID 28017832, 2017).
steatosis (1 paper, 2022). Increased lipid within the cytoplasm of cells. "Interestingly Vps33b liver specific knockout (with a liver-specific Vps33b gene mutation) demonstrated focal steatosis in their liver suggesting defects of lipid metabolism." (PMID 36429129, 2022).
tumor (7 papers, 2019 to 2024). "And the high expression of Circ-VPS33B was associated with tumor size, TNM stage and lymphatic metastasis in GC patients." (PMID 39816354, 2024). "Loss of VPS33B has been associated with hepatocarcinogenesis in a VPS33B-knockout mouse model, attributable to loss of a tumour suppressor effect." (PMID 36010647, 2022). "Altogether, we can conclude that Circ-VPS33B promotes tumor growth and the Warburg effect through the miR-873-5p/HNRNPK axis." (PMID 39816354, 2024). "Taken together, these data suggested that VPS33B acted as a potential tumor suppressor that participated in the suppression of the EGFR/PI3K/AKT-induced cell cycle signaling cascade." (PMID 30944308, 2019). "VPS33B expression was negatively correlated with the TNM (tumor, node, metastasis) stage (P < 0.001; I–II vs. III–IV), M stage (P = 0.019; M0 vs. M1), and smoking (P = 0.048; Yes vs. No)." (PMID 30944308, 2019). "Moreover, cellular transport was also compromised in tumor cells through downregulation of 38 proteins related to vesicle-mediated transport, as well as important proteins involved in vesicle docking involved in exocytosis (such as VPS33B, RAB3D, VAMP3, and SCFD1)." (PMID 39202022, 2024). "In previous studies, we also observed that miR-133a-3p, miR-5188, miR-3188, miR-374a, and miR-296-3p, respectively were modulated by VPS33B, HBx, FOXO1, PDCD4, and HDGF involving in the tumor pathogenesis induced by these genes." (PMID 32641685, 2020). "Therefore, VPS33B would promote exosomes carrying CT62, DPY19L2P1, and KCNH1‐IT1 to other cells, thus regulating the tumour microenvironment." (PMID 35194922, 2022). "Therefore, VPS33B would promote exosomes carrying CT62, DPY19L2P1 and KCNH1‐IT1 to other cells, thus regulating the tumor microenvironment." (PMID 35194922, 2022). "Furthermore, another tumor suppressor, NESG1, interacted with VPS33B by colocalizing in the cytoplasm." (PMID 30944308, 2019). "VPS33B has been reported as a tumor suppressor only in HCC17, but the precise mechanism of its tumor-inhibitory effect remains unclear." (PMID 30944308, 2019).
cancer (5 papers, 2019 to 2025). A tumor composed of atypical neoplastic, often pleomorphic cells that invade other tissues. "The likely role of VPS33B in cancer progression and invasiveness is not limited to the liver." (PMID 36010647, 2022). "The vacuolar protein sorting 33B (VPS33B) was rarely reported in malignant tumors." (PMID 30944308, 2019). "Extensive research has been conducted on the role of METTL16 in regulating cancer progression through m6A modification of target genes, including U6 snRNA, MALAT1, XIST, and RAB11B‐AS1, and mRNA (MAT2A, VPS33B, FGFR4, and GPX4)." (PMID 40095756, 2025). "The discovery that VPS33B is required for collagen fibril formation but not collagen protomer secretion highlights an important distinction between ‘collagen secretion’ and ‘collagen fibrillogenesis’, especially in the context of collagen pathologies (e.g. fibrosis, cancer metastasis)." (PMID 39812558, 2025).
bacterial infection (1 paper, 2018). "We hypothesize that this interaction may be enhanced upon the addition of an external stimulus, for example during bacterial infection, when VPS33B/VIPAR activity has been demonstrated to be important for a robust immunological response." (PMID 29778605, 2018).
VPS33B also shares sentences with these, for which no sentence is quoted: renal dysfunction (6 papers); arthrogryposis-renal dysfunction-cholestasis syndrome (3); renal tubular dysfunction (2); autism (1); congenital neutropenia (1); cyst (1); Fanconi syndrome (1); Glucose intolerance (1); hepatocellular carcinoma (1); lung fibrosis (1); lymphedema (1); myocardial infarction (1); Obesity (1); ovarian carcinoma (1); progressive familial intrahepatic cholestasis 1 (1); renal tubular acidosis (1).